CDK6-AS1 (CDK6 antisense RNA 1)
Synonyms: BALR-2; AC002454.1
Gene: Long non-coding RNA gene on chromosome 7 (92,835,960 to 92,918,848, forward strand). Ensembl gene ENSG00000237819.
Diseases named in the same sentence as CDK6-AS1 in open-access papers:
CDK6-AS1 is named in the same sentence as 3 diseases in open-access papers, as found by Europe PMC text mining. Sharing a sentence is not in itself a finding about the gene and the disease.
CDK6-AS1 shares sentences with these, for which no sentence is quoted: cancer (1 paper); endometriosis (1); leukemia (1).